UBN2 (ubinuclein 2)
Synonyms: KIAA2030; FLJ25778
Tractability: PROTAC: UniProt records ubiquitination sites on it; ubiquitination databases record sites on it; its protein half-life has been measured.
Gene: Protein-coding gene on chromosome 7 (139,230,356 to 139,308,236, forward strand). Ensembl gene ENSG00000157741.
Subcellular location (Human Protein Atlas): Nucleoplasm
Gene Ontology:
Molecular function: protein binding
Biological process: nucleosome assembly; regulation of chromatin organization
Cellular component: extracellular region; HIR complex; nucleoplasm
Genetic constraint (gnomAD): Loss-of-function variants: 24 observed, 93.26 expected, observed/expected ratio (o/e) 0.26, 90% interval 0.19 to 0.36. The upper end of that interval is the gene's LOEUF score, 0.36, which puts it in group 1 of 6, group 1 being the genes least tolerant of losing a copy. Missense variants: 1,582 observed, 1,524.7 expected, observed/expected ratio (o/e) 1.04, 90% interval 1 to 1.08. Synonymous variants: 631 observed, 586.34 expected, observed/expected ratio (o/e) 1.08, 90% interval 1.01 to 1.15.
Homologues: Orthologues: chimpanzee UBN2 (99% identical), macaque UBN2 (99% identical), pig UBN2 (93% identical), dog UBN2 (92% identical), rat Ubn2 (91% identical), mouse Ubn2 (91% identical), guinea pig UBN2 (85% identical), rabbit UBN2 (78% identical), tropical clawed frog ift56 (56% identical), zebrafish ubn2b (34% identical), zebrafish ubn2a (33% identical). Paralogues in human: UBN1 (33% identical).
Diseases named in the same sentence as UBN2 in open-access papers:
UBN2 is named in the same sentence as 7 diseases in open-access papers, as found by Europe PMC text mining. Sharing a sentence is not in itself a finding about the gene and the disease. The quoted sentences say what the papers report.
autism (2 papers, 2021 to 2022). Persistent deficits in social interaction and communication and interaction as well as a markedly restricted repertoire of activity and interest as well as repetitive patterns of behavior. "We found differential expression of autism-relevant genes in our DE gene list that are also associated with cell adhesion (Dscam, Reln) or gene regulation (Kat2b, Kmt2c, Med13/Med13l, Tbl1xr1, Ubn2)." (PMID 33757588, 2021).
colorectal cancer (1 paper, 2019). A primary or metastatic malignant neoplasm that affects the colon or rectum. "The molecular role and mechanism of UBN2 in the development and progression of cancers, including colorectal cancer (CRC), is not well understood." (PMID 31110467, 2019).
lung carcinoma (1 paper, 2018). "For example, MALAT1, a critical regulator of the metastasis phenotype in lung cancer cells, potentially regulated the expression of UBN2 and NEAT1 (row two)." (PMID 29303984, 2018).
lymph node metastasis (1 paper, 2019). "High expression of UBN2 correlated to aggressive characteristics (e.g. lymph node metastasis and distant metastasis) and poor patient survival." (PMID 31110467, 2019). "However, high UBN2 expression was significantly correlated with advanced clinical stage (p = 0.044), lymph node metastasis (p = 0.037) and distant metastasis (p = 0.025)." (PMID 31110467, 2019). "In addition, overexpression of UBN2 notably correlated with the invasive and aggressive features, including advanced clinical stage, lymph node metastasis, distant metastasis, high proliferation index and poor prognosis." (PMID 31110467, 2019).
tumor (4 papers, 2017 to 2025). "UBN2 is widely expressed in tumor tissues and encodes a nuclear protein that interacts with viral and cellular transcription factors." (PMID 31110467, 2019). "qRT–PCR revealed that the tumor/normal (T/N) ratio of UBN2 mRNA levels was higher than 1.5-fold in 77% (23/30) of the tumors, with the highest increase of 24-fold." (PMID 31110467, 2019). "Subcutaneous tumorigenesis assay demonstrated that knockdown of UBN2 significantly inhibited tumor growth in nude mice (p < 0.01)." (PMID 31110467, 2019). "Oncomine network and The Cancer Genome Atlas (TCGA) database were downloaded and Gene Set Enrichment Analysis (GSEA) was performed to compare the UBN2′s expression between normal and tumor tissues, as well as the potential correlation of UBN2 expression with signaling pathways." (PMID 31110467, 2019). "The current study demonstrates that UBN2 promotes tumor progression in CRC." (PMID 31110467, 2019). "UBN2 may promote proliferation, tumor growth and invasion partially via regulation of the Ras/MAPK signaling pathway." (PMID 31110467, 2019). "Similarly, mice bearing mouse G3 MB tumor cells over-expressing Smyd1 or Ubn2 survived with similar latency compared to tumor cells transduced with empty vector (upper right and lower left)." (PMID 29029386, 2017). "There were four non-silent mutations in this tumor, all missense SNVs: Lrfn2 R656H, Smyd1 R237Q, Ubn2 Q549K and Wdr11 I46T." (PMID 29029386, 2017). "Comparative analysis revealed tumor-specific upregulation of GLRX3, IL1RN, and TNFRSF4 (p < 0.001), contrasting with downregulation of FCGRT, UBN2, and WNT5B in EC versus normal tissues." (PMID 40722666, 2025). "In conclusion, miR-8485-mediated downregulation of UBN2, ETS1, MMS22L, GSK3B, and SLC44A1 inhibits tumor progression through mechanisms involving cell cycle arrest, metastasis inhibition, apoptosis induction, and choline metabolism." (PMID 40095604, 2025). "Indeed, enforced expression of wild-type WDR11 (but not LRFN2, Ubn2, Smyd1) hindered G3 MB development, which is in-line with our hypothesis about its tumor suppressor activity." (PMID 29029386, 2017).
cancer (2 papers, 2019 to 2023). A tumor composed of atypical neoplastic, often pleomorphic cells that invade other tissues. "UBN1, an important paralog gene of UBN2 that encodes a partial ubinuclein polypeptide, was aberrantly expressed in many human cancers, including leukemia, CRC, lung carcinoma, cervical carcinoma, melanoma, as well as pancreatic adenocarcinoma." (PMID 31110467, 2019). "UBN2 is targeted by miR-575 as an oncomir that can boost cell proliferation and migration in some cancer cells and possibly chronic ATLL." (PMID 36978083, 2023). "However, the expression and function of UBN2 in cancers is not known." (PMID 31110467, 2019).
UBN2 also shares sentences with these, for which no sentence is quoted: neurodegenerative disease (1 paper).